SMARCB1 (SWI/SNF related BAF chromatin remodeling complex subunit B1)
Diseases named in the same sentence as SMARCB1 in open-access papers (continued):
Sharing a sentence is not in itself a finding about the gene and the disease.
schwannoma (43 papers, 2008 to 2025). A benign, usually encapsulated slow growing tumor composed of Schwann cells. "The analysis of a schwannoma in this patient indicated somatic loss of the wild-type SMARCB1 allele, in combination with NF2 loss." (PMID 40794298, 2025). "The co-involvement of SMARCB1 and NF2 in the pathogenesis underlying schwannomas in patients with SMARCB1-related SWN is substantiated by mouse models of schwannoma development (Sect." (PMID 40794298, 2025). "In contrast to schwannomas, complete loss of SMARCB1 protein expression as determined by immunohistochemistry is frequently observed in MRTs." (PMID 40794298, 2025). "In any case, the key point to be taken from the four-hit/three-step model is that biallelic SMARCB1 loss is insufficient for schwannoma growth in patients with SMARCB1-related SWN." (PMID 40794298, 2025). "Additional scRNA-seq analyses of schwannomas from patients with characterized germline variants in either SMARCB1 or LZTR1 would be instructive in order to elaborate any transcriptome differences that remain to be identified." (PMID 40794298, 2025). "Whilst biallelic NF2 gene inactivation is an absolute requirement for schwannoma growth in addition to biallelic SMARCB1 mutation, complete NF2 gene inactivation is dispensable for MRT development." (PMID 40794298, 2025). "The severe phenotype of both patients suggests that at least some patients with CSS and SMARCB1 PVs are at risk of developing schwannomas and should be investigated by MRI to prevent severe problems caused by a delayed diagnosis of the tumours." (PMID 40794298, 2025). "The subsequent somatic hits occur in the schwannoma: two hits lead to the loss of the region of chromosome 22 containing the SMARCB1 and NF2 alleles (step 2), and the final hit mutates the remaining NF2 allele (step 3)." (PMID 39170644, 2024). "We describe a case of a 28-year-old woman with a confirmed diagnosis of CSS and SMARCB1 mutation who presents with multiple schwannomas and an intra-abdominal neurofibroma." (PMID 39170644, 2024). "Loss of SMARCB1 (INI1) expression is found in epithelioid schwannoma, or a mosaic pattern of SMARCB1 (INI1) expression indicates syndrome-associated schwannoma." (PMID 37046591, 2023). "In SMARCB1 (INI1) mutation-positive schwannomas, additional genetic alterations can occur, including losing one copy of chromosome 22 and inactivating mutations in the NF2 gene." (PMID 35291225, 2022). "Cancer-associated mutations within the CTD have also been found in meningioma, adenocarcinoma, and schwannoma, particularly R374Q and R377H, but low-frequency cancer-associated mutations are found throughout SMARCB1." (PMID 35892904, 2022). "This proposition is further corroborated by the wide spectrum of tumours, including more benign entities, such as Schwannomas, that pathogenic germline mutations in SMARCB1 (and related genes) predispose to29." (PMID 33658498, 2021). "On the other hand, they proposed MRI surveillance for patients with a germline missense mutation of SMARCB1 to allow the early detection of schwannomas." (PMID 33692948, 2021). "In SMARCB1 (INI1) mutation-positive schwannomas, there can be additional genetic alterations, including loss of one copy of chromosome 22 and inactivating mutations in the NF2 gene." (PMID 34072574, 2021). "Loss of SMARCB1 was also related to Schwannoma, another phenotype found in NF1 despite being more frequent in NF2." (PMID 32858845, 2020). "Frequent loss of the second allele in combination with biallelic loss of NF2 has been reported in such tumor tissues, indicating that SMARCB1 acts as a tumor suppressor in schwannomas and that the familial SMARCB1 mutations lead to a loss-of-function." (PMID 31273213, 2019). "This is concluded from the observation of frequent somatic, tumour-specific NF2 mutations, and the loss of the second NF2 allele in schwannomas from patients with germline SMARCB1 mutations." (PMID 27921248, 2017).
schwannoma (continued). "We also defined an early spatio-temporal window during which Smarcb1 loss results in malignant tumor formation and showed that biallelic Nf2 loss is necessary and Smarcb1 loss is dispensable for schwannoma formation." (PMID 28824165, 2017). "LOH analysis indicated that the mutant SMARCB1 allele was retained in two schwannomas and the leiomyosarcoma of the patient, whereas the wild-type allele was lost, indicative of biallelic SMARCB1 inactivation in both types of tumour." (PMID 27921248, 2017). "The chromosome 22 carrying the mutant SMARCB1 allele was retained in the pRCC1 and in schwannomas from this patient, whereas the wild-type SMARCB1 allele and one NF2 copy were lost by deletion." (PMID 27921248, 2017). "In a second schwannoma from the same individual, the partial loss of the SMARCB1 wild-type allele was observed." (PMID 27921248, 2017). "Patients with germline mutations of the SMARCB1 gene are predisposed to develop RTs or schwannomas, two tumor types with dramatically different clinical features." (PMID 28824165, 2017). "The four-hit, three-step model of tumorigenesis of schwannomas from SMARCB1 positive patients forced us to perform an exhaustive mutational analysis of both SMARCB1 and NF2 genes, since they are somatically inactivated in both alleles." (PMID 25739810, 2015). "This retention of partial function by N-terminal truncations mediated by the use of alternative methionine start sites may also explain the mosaic SMARCB1 protein expression pattern in schwannomas harbouring these variants." (PMID 40794298, 2025). "Finally, the fourth hit (third step) involves a tumour-specific pathogenic variant of the NF2 gene located in cis to the SMARCB1 germline PV that leads to biallelic NF2 inactivation driving schwannoma development." (PMID 40794298, 2025). "Importantly, the 22q LOH affects the chromosome harbouring the wild-type SMARCB1-allele and hence occurs in trans to the germline SMARCB1 PV which is retained in the schwannoma." (PMID 40794298, 2025). "As a disease, it is classified by at least one schwannoma confirmed pathologically and a common variant of SMARCB1, LZTR1, or loss of heterozygosity at chromosome 22q in two anatomically separate schwannomas and without the presence of bilateral vestibular schwannomas." (PMID 41001135, 2025). "In addition, the tumor-suppressor SMARCB1 at 22q11.2 has been implicated in the pathogenesis of schwannomas in selected cases." (PMID 41300852, 2025). "In the epithelioid histopathologic subtype of MPNST, a rare tumor with diffuse S-100 positivity, infrequent association with NF1, and occasional malignant transformation from schwannoma, mutations in SMARCB1 have also been observed in two-thirds of patients evaluated (n = 63)." (PMID 37173979, 2023). "Schwannomas in patients with germline SMARCB1 mutations have been reported to exhibit a mosaic SMARCB1 protein expression pattern by immunohistochemical staining of tumour sections with the monoclonal BAF47 antibody specific for the C-terminal part of SMARCB1 raised against amino acids 257–359." (PMID 27921248, 2017). "The mosaic expression pattern may be explicable in terms of a subset of schwannoma cells retaining the wild-type SMARCB1 allele, thereby enabling the synthesis of sufficient SMARCB1 protein to give rise to positive immunostaining of the respective nuclei." (PMID 27921248, 2017). "However, families with RTs or multiple epitheloid schwannomas sharing the same SMARCB1 mutation have also been described." (PMID 28824165, 2017). "Consequently, the mutational mechanism would appear to be similar to the 4-hit/3-step model of tumorigenesis observed in schwannomas of patients with germline SMARCB1 mutations." (PMID 27921248, 2017). "Similar to SMARCB1-related schwannomas, different additional somatic mutations in NF2 were identified in schwannomas from these patients, thus supporting the 4-hit/3-step hypothesis." (PMID 28824165, 2017).
schwannoma (continued). "However, SMARCB1-associated schwannomas follow a four-hit, three-step model, in which both alleles of SMARCB1 and NF2 genes are inactivated in the tumor, with one of the steps being always the loss of a big part of chromosome 22 involving both loci." (PMID 25739810, 2015). "Both the type of pathogenic SMARCB1 variant and whether it leads to the complete loss or only the partial loss-of-function determines which type of tumour develops, either rhabdoid tumour (RT) or schwannoma." (PMID 40794298, 2025). "Thus, both patients developed schwannomas despite having different SMARCB1 pathogenic variants." (PMID 39170644, 2024). "Since the LOH events in SMARCB1 mutation-positive schwannoma usually include large parts of 22q, other tumour suppressor genes located on 22q will also be haploinsufficient and this may contribute to schwannoma growth." (PMID 27921248, 2017). "It is likely that additional genetic alterations drive malignant transformation of schwannomas in patients with SMARCB1-related SWN." (PMID 40794298, 2025). "Most likely, larger numbers of SWN-schwannomas should be analysed comparatively in order to identify any molecular differences between schwannomas derived from patients with either LZTR1- or SMARCB1-related SWN." (PMID 40794298, 2025). "Several studies have indicated that the proportion of schwannomas in patients with SMARCB1-related SWN exhibiting chromosome 22q LOH (chr.22q-LOH) is very high." (PMID 40794298, 2025). "Further studies, including higher numbers of schwannomas from patients with SMARCB1-related SWN, will be necessary to identify the full spectrum of pathways altered in these tumours." (PMID 40794298, 2025). "By contrast, hypomorphic SMARCB1 PVs during later developmental stages affecting more differentiated Schwann cell precursors give rise to schwannomas." (PMID 40794298, 2025). "Mutations in SMARCB1 or LZTR1 disrupt their normal functions, leading to the formation of multiple schwannomas." (PMID 40764996, 2025). "This is supported by immunohistochemical staining studies of SMARCB1 protein in schwannomas from people with familial schwannomas, which typically show a mosaic pattern of staining, indicating protein expression in some cells but not others." (PMID 41284083, 2025). "In patients with SMARCB1-related SWN, the four-hit/three‐step model appears to underlie the vast majority of schwannomas." (PMID 40794298, 2025). "By contrast, the molecular signature of schwannomas from patients with genetically confirmed LZTR1- or SMARCB1-related SWN has been analysed so far only in a single study." (PMID 40794298, 2025). "Instead, tumorigenesis of schwannomas in patients with SMARCB1‐ (and LZTR1-) related SWN appears to follow a four‐hit/three‐step model that includes somatic biallelic inactivation of the NF2 gene." (PMID 40794298, 2025). "Major criteria for the diagnosis of SWN are at least one pathologically confirmed schwannoma or HNST and an SMARCB1 or LZTRK1 pathogenic variant in unaffected tissue (e.g., blood) or a shared SMARCB1 or LTRK1 pathogenic variant in two schwannomas or HNST." (PMID 37046591, 2023). "In humans, it was highlighted that also the inactivation of other tumor suppressor genes, such as LZTR1, COQ6 and SMARCB1, is correlated to the schwannoma formation." (PMID 37741837, 2023). "In particular, it was evidenced that the SWI/SNF chromatin-remodeling complex (i.e., the eukaryotic analog of SMARCB1) possesses and important role for the schwannoma development." (PMID 37741837, 2023). "The new classification of schwannomatoses is based on the coupling of the causative genes (i.e., NF2, SMARCB1 and LZTR1) and on the histological hallmark of these syndromes (i.e., schwannomas)." (PMID 35741273, 2022). "Mosaic loss of immunohistochemical expression of SMARCB1/INI1 is a reliable marker of SWN and can assist in distinguishing SWN from an isolated schwannoma." (PMID 34072574, 2021).
schwannoma (continued). "Although biallelic mutations of SMARCB1 or LZTR1 have been detected in the patients with SWN, the classical two-hit model of tumorigenesis is insufficient to account for schwannoma growth, since NF2 is frequently inactivated in these tumors." (PMID 34072574, 2021). "Lastly, although the functions of INI1/SMARCB1 and LZTR1 in schwannomagenesis are still unclear, recent research shows that subsequent biallelic loss of Nf2 is necessary to induce schwannoma formation." (PMID 32960816, 2020). "Despite the identification of causative genes, including NF2 (Merlin), INI1/SMARCB1, and LZTR1, the exact molecular mechanism of schwannoma development is still poorly understood." (PMID 32960816, 2020). "Most of these studies were performed before having a clear picture of the four-hit, three-step model, that SMARCB1 positive patients exhibit in their schwannomas." (PMID 25739810, 2015). "Furthermore, immunohistochemical analysis has indicated that N-terminally truncated SMARCB1 proteins are expressed in schwannomas of the respective patients harbouring exon 1 PVs." (PMID 40794298, 2025). "MRI is used to identify schwannomas and rule out vestibular schwannomas, while genetic testing focuses on identifying mutations in the SMARCB1 and LZTR1 genes." (PMID 40764996, 2025). "Remarkably, 57% of patients clinically diagnosed with non-NF2-related SWN but without germline LZTR1 or SMARCB1 lesions exhibit mosaic NF2-related SWN as determined by identical pathogenic NF2 variants detected in two independent schwannomas." (PMID 40794298, 2025). "Smarcb1 loss and biallelic Nf2 inactivation at later stages of Schwann cell development (starting at E13.5) lead to benign schwannomas but not rhabdoid tumours." (PMID 40794298, 2025). "In a total of 153 patients aged younger than 24 years with an isolated schwannoma, genetic testing indicated that 15 (9.8%) patients had a germline NF2 pathogenic variant, six patients (3.9%) had a germline SMARCB1 PV, and 10 patients (6.5%) had a germline LZTR1 PV." (PMID 40794298, 2025). "Of note, mitotic recombination has been excluded as the mechanism causing 22q LOH in schwannomas of patients with germline SMARCB1 PVs." (PMID 40794298, 2025). "Interestingly, emerging evidence has highlighted the role of SMARCB1/INI1 in schwannoma pathogenesis." (PMID 40666544, 2025). "Isolated schwannomas in patients with SMARCB1-, LZTR1- or NF2-related SWN may already be present in early childhood or in young adults." (PMID 40794298, 2025). "Likewise, schwannomas of patients with SMARCB1- and LZTR1-related SWN exhibit biallelic NF2 gene inactivation as mentioned in the previous section." (PMID 40794298, 2025). "Indeed, several studies have observed that schwannomas in patients with germline SMARCB1 PVs exhibit a mosaic SMARCB1 protein expression pattern as determined by immunohistochemistry." (PMID 40794298, 2025). "Whether nuclear export of mutant SMARCB1 also contributes to the development of schwannomas or other tumours in patients with SMARCB1-related SWN is currently unknown." (PMID 40794298, 2025). "This conclusion is in accord with the finding that conditional Smarcb1 knockout mice do not develop schwannomas, indicating that biallelic Smarcb1 loss is not on its own sufficient for the growth of schwannomas." (PMID 40794298, 2025). "Furthermore, schwannomas of patients with SMARCB1- and LZTR1-related SWN are phenotypically and histopathologically indistinguishable from schwannomas of patients with NF2-related SWN and sporadic schwannomas." (PMID 40794298, 2025). "Although NF2 and SMARCB1 mutations have been reported in schwannomas from other anatomical sites, we did not observe these aberrations." (PMID 37535242, 2023). "However, the high frequency of LoF LZTR1 variants in the general population suggests that LZTR1 variants confer a reduced risk of schwannomas compared to germline NF2 and SMARCB1 pathogenic variants, making classification of novel variants challenging." (PMID 35391499, 2022).
schwannoma (continued). "Interestingly, even though these schwannomas show some rhabdoid features and loss of INI1/BAF47 staining, they are distinct from MPNST with SMARCB1 loss." (PMID 33532948, 2021). "We tested the hypothesis that Smarcb1 inactivation in NCCs and in the SC lineage is sufficient to initiate schwannoma development in the mouse." (PMID 28824165, 2017). "Although this scenario may account for some schwannomas, it cannot explain the mosaic SMARCB1 immunostaining observed in the majority of these tumours." (PMID 27921248, 2017). "Patients with Coffin–Siris syndrome and germline SMARCB1 mutations have been previously reported, but none have exhibited schwannomas." (PMID 27921248, 2017). "The existence of adult carriers of a SMARCB1 mutation without RT in families presenting either RTs or schwannomas suggests the existence of a specific developmental time window during which RT progenitor cells are vulnerable to SMARCB1 loss." (PMID 28824165, 2017). "The observation that LOH in schwannomas of patients with SMARCB1 germline mutations is not mediated by mitotic recombination supports the 4-hit/3-step model of tumorigenesis from the standpoint of maximum parsimony." (PMID 27921248, 2017). "Somatic mosaicism for the SMARCB1 mutation in the family members affected only by schwannomas cannot explain the absence of rhabdoid tumours in these patients." (PMID 27921248, 2017). "Since this degradation is likely to be a random process, some cells may still express detectable amounts of SMARCB1 protein resulting in a mosaic expression pattern when analysing schwannoma tissue sections." (PMID 27921248, 2017). "Furthermore, 29% (37/125) of all schwannomas harboured inactivating mutations in either ARID1A or ARID1B, which along with SMARCB1, encode proteins of the SWI/SNF chromatin-remodeling complex." (PMID 27921248, 2017). "Surprisingly, complete loss of Smarcb1 in the mGFAP-Cre;Smarcb1flox/flox;Nf2flox/flox tumors did not result in increased cell proliferation compared to schwannoma tumorlets in DRGs from mGFAP-Cre;Nf2flox/flox mice." (PMID 28824165, 2017). "An exhaustive molecular genetic analysis was performed in two schwannomas of the patient to identify mutations in the NF2 and SMARCB1 genes, including cDNA and DNA sequencing, MLPA, microsatellite multiplex PCR and SNP-array analyses, to clarify the molecular diagnostics." (PMID 25739810, 2015). "However, schwannomas from SMARCB1 positive patients follow a four-hit, three-step model of tumorigenesis in which both alleles of SMARCB1 and NF2 genes are inactivated in the tumor." (PMID 25739810, 2015). "However, it is unknown if RAS/MAPK pathway activation also plays an important role in schwannomas of patients with SMARCB1-related SWN." (PMID 40794298, 2025). "Furthermore, both schwannomas were negative for SMARCB1 immunostaining, indicative of a complete loss of the SMARCB1 protein." (PMID 27921248, 2017). "Such hypomorphic pathogenic SMARCB1 variants may explain why patients with these variants and SMARCB1-related SWN exhibit benign schwannomas during adulthood but usually do not develop the highly malignant pediatric AT/RT characterized by the complete loss-of-function of SMARCB1 (Sect." (PMID 40794298, 2025). "The molecular mechanism underlying the tumorigenesis of schwannomas in patients with SMARCB1- (and LZTR1-) related SWN is clearly not in agreement with the classic Knudson two‐hit model hypothesis involving the biallelic inactivation of a single tumour suppressor gene." (PMID 40794298, 2025). "The basis of the four-hit/three-step model is that all three tumour suppressor genes known to be relevant to schwannoma development, namely NF2, LZTR1 and SMARCB1, are located on chromosome 22q." (PMID 40794298, 2025). "However, not all schwannomas from patients with LZTR1 germline mutations exhibit this pattern of mutational events similar to that observed in some schwannomas of patients with germline SMARCB1 mutations." (PMID 27921248, 2017).